CUX1 (cut like homeobox 1)
Description:
May be involved in intra-Golgi retrograde transport. Transcription factor involved in the control of neuronal differentiation in the brain. Regulates dendrite development and branching, and dendritic spine formation in cortical layers II-III. Also involved in the control of synaptogenesis. In addition, it has probably a broad role in mammalian development as a repressor of developmentally regulated gene expression. May act by preventing binding of positively-activing CCAAT factors to promoters. Component of nf-munr repressor; binds to the matrix attachment regions (MARs) (5' and 3') of the immunoglobulin heavy chain enhancer. Represses T-cell receptor (TCR) beta enhancer function by binding to MARbeta, an ATC-rich DNA sequence located upstream of the TCR beta enhancer. Binds to the TH enhancer; may require the basic helix-loop-helix protein TCF4 as a coactivator. [CDP/Cux p110]: Plays a role in cell cycle progression, in particular at the G1/S transition. As cells progress into S phase, a fraction of CUX1 molecules is proteolytically processed into N-terminally truncated proteins of 110 kDa. While CUX1 only transiently binds to DNA and carries the CCAAT-displacement activity, CDP/Cux p110 makes a stable interaction with DNA and stimulates expression of genes such as POLA1.
Synonyms: CDP; CUTL1; CDP1; CUX; CUT; Clox; CDP/Cut; CDP/Cux; Cux/CDP; CASP; GOLIM6; COY1; GDDI; NEDDMS; Nbla10317; p100; p110; p200; p75
Tractability: PROTAC: UniProt records ubiquitination sites on it; ubiquitination databases record sites on it; its protein half-life has been measured.
Gene: Protein-coding gene on chromosome 7 (101,815,904 to 102,283,958, forward strand). Ensembl gene ENSG00000257923.
Subcellular location: Golgi apparatus membrane; Nucleus
Subcellular location (Human Protein Atlas): Golgi apparatus; Nucleoplasm
Pathways (Reactome):
Disease: Signaling by FGFR1 in disease; Signaling by cytosolic FGFR1 fusion mutants
Vesicle-mediated transport: Intra-Golgi traffic
Gene Ontology:
Molecular function: sequence-specific DNA binding; sequence-specific double-stranded DNA binding; DNA-binding transcription factor activity, RNA polymerase II-specific; RNA polymerase II transcription regulatory region sequence-specific DNA binding; DNA binding
Biological process: negative regulation of transcription by RNA polymerase II; positive regulation of dendrite morphogenesis; regulation of transcription by RNA polymerase II; regulation of DNA-templated transcription
Cellular component: Golgi apparatus; nucleoplasm; nucleus; chromatin; cytosol
Genetic constraint (gnomAD): Loss-of-function variants: 29 observed, 142.5 expected, observed/expected ratio (o/e) 0.2, 90% interval 0.15 to 0.28. The upper end of that interval is the gene's LOEUF score, 0.28, which puts it in group 1 of 6, group 1 being the genes least tolerant of losing a copy. Missense variants: 1,450 observed, 1,813.5 expected, observed/expected ratio (o/e) 0.8, 90% interval 0.76 to 0.83. Synonymous variants: 800 observed, 772.49 expected, observed/expected ratio (o/e) 1.04, 90% interval 0.98 to 1.1.
Cancer hallmarks: escaping immune response to cancer (promotes); genome instability and mutations (promotes); invasion and metastasis (promotes); suppression of growth (promotes); genome instability and mutations (suppresses); proliferative signalling (promotes); angiogenesis (promotes); escaping programmed cell death (promotes)
Homologues: Orthologues: chimpanzee CUX1 (99% identical), macaque CUX1 (99% identical), dog CUX1 (92% identical), pig CUX1 (92% identical), rat Cux1 (90% identical), mouse Cux1 (90% identical), guinea pig CUX1 (84% identical), tropical clawed frog cux1 (80% identical), rabbit CUX1 (71% identical), zebrafish cux1a (60% identical), Drosophila melanogaster ct (27% identical), Caenorhabditis elegans cone-1 (23% identical). Paralogues in human: CUX2 (43% identical).
Diseases named in the same sentence as CUX1 in open-access papers:
CUX1 is named in the same sentence as 115 diseases in open-access papers, as found by Europe PMC text mining. Sharing a sentence is not in itself a finding about the gene and the disease. The quoted sentences say what the papers report.
breast cancer (23 papers, 2007 to 2025). A primary or metastatic malignant neoplasm involving the breast. "Over-expression of short p75 or p110 CUX1 isoforms in fibroblasts and breast cancer cells causes increased proliferation, cell cycle progression, and tumor formation in vivo." (PMID 34997000, 2022). "CUX1 also has distinct splice variants; the p75CUX1 isoform of the transcription factor has been associated with breast cancer and myeloid leukaemia." (PMID 32180898, 2020). "Elevated CUX1 expression in a transgenic mouse model enables the emergence of mammary tumors with spontaneous activating Kras mutations." (PMID 24618719, 2014). "These three TFs play important roles in breast cancer development and progression: CUX1 is associated with poor prognosis in ER-positive breast cancer, NR4A1 promotes tumor cell metastasis, and IKZF3 is linked to poor prognosis in HER2+ and regulates cell proliferation." (PMID 40923764, 2025). "In accordance with our results, recent studies have reported that CUX1 overexpression was significantly associated with tumorigenesis and poor prognosis in patients with multiple myeloma, uterine leiomyomas, colorectal cancer, and high-grade breast cancer." (PMID 34422906, 2021). "CUX1 is knocked by siRNAs in radioresistant breast cancer cells and MEFs (mouse embryonic fibroblasts)." (PMID 34900673, 2021). "When expressed under the control of the mouse mammary tumor virus long terminal repeat (MMTV-LTR) promoter, p200 CUX1 induced mammary tumors with a long latency." (PMID 34070180, 2021). "In line with our findings, the importance of p110 CUX1 as a facilitator of tumor development and progression has recently been demonstrated in several other tumor models, including breast cancer and glioma." (PMID 34070180, 2021). "Many lines of evidence have indicated that overexpression of CUX1 was present in various types of cancers, such as melanoma, pancreatic cancer, multiple myeloma, and breast cancer." (PMID 34422906, 2021). "A role for CUX1 in DNA repair was first suggested from the analysis of mammary tumors that develop in MMTV-CUX1 transgenic mice." (PMID 34204734, 2021). "Our data are in line with several reports in the literature describing CUX1 as important trigger of carcinogenesis in various solid tumor entities including glioma, neuroblastoma and breast cancer." (PMID 34070180, 2021). "For example, by cooperating with GLIS1, CUX1 can stimulate autocrine activation of the Wnt/β-catenin pathway to enhance cell migration and invasion in breast cancer." (PMID 32547943, 2020). "Elevated expression of CUX1 was observed and positively associated with poor prognosis in CRC, high-grade breast cancer, and pancreatic cancer." (PMID 33014778, 2020). "CUX-1 has been shown to play a role in breast cancer progression and in drug resistance in gastric cancer but to date has minimal functional association with prostate cancer." (PMID 32180898, 2020). "Studies in breast cancer have identified an association between elevated CUX1 expression and tumour progression and CUX1 expression was inversely correlated with relapse-free and overall survival in a small subset of breast cancer tissues." (PMID 32180898, 2020). "The mechanisms by which CUX1 promotes tumor development have been investigated in many types of cancers especially in breast cancer and pancreatic cancer." (PMID 32547943, 2020). "For example, MMTV-p110, p75 transgenic mice developed mammary tumors after a long latency period, and genes involved in Wnt/β-catenin signaling were directly regulated by those short CUX1 isoforms." (PMID 32547943, 2020). "As the upstream of FGF1/HGF signaling pathway, CUX1 has been reported to contribute to the progression of luminal and basal breast cancer, help distinguishing Her2 subtype of breast cancer." (PMID 31480430, 2019).
breast cancer (continued). "For example, the TGFβ-Smad pathway induces the expression of interleukin-11 (IL-11), connective tissue growth factor (CTGF), angiopoietin-like 4 (ANGPTL4), and cut-like homeobox 1 (CUTL1) to promote breast cancer invasion and metastasis." (PMID 28356139, 2017). "Expression profiling analysis in human and mouse mammary tumors suggested that high Wnt gene expression requires both CUX1 and GLIS1." (PMID 25217618, 2014). "Overall, A correlation between CUX1 and WNT levels was observed in the 3 out of 3 breast cancer datasets that had a relevant CUX1 probe (Esserman, Gluck, TCGA), and between Glis1 and WNT in 7 out of 8 datasets with Glis1 probes." (PMID 25217618, 2014). "Mammary tumors developed in 20.9% of p200 CUX1 transgenic lines as compared to 2.4% of wild-type FVB/N mice." (PMID 24618719, 2014). "We did not, however, observe the upregulation of stem or progenitor cell markers in mammary tumors that otherwise displayed Glis1, CUX1 and Wnt expression." (PMID 25217618, 2014). "For example, CUX1 did not stimulate the expression of WNT5A in MCF10A cells, although this gene was upregulated in two MMTV-CUX1 mammary tumors and was previously reported to be activated by CUX1 in the PANC1 and HT1080 cell lines." (PMID 25217618, 2014). "In summary, mammary-specific p200 CUX1 expression increased the incidence of late-onset mammary tumors of various histological types." (PMID 24618719, 2014). "Meta-analysis of human breast cancer datasets showed that elevated WNT gene expression also correlated with high levels of CUX1 and GLIS1." (PMID 25217618, 2014). "We previously reported that MMTV-p110 CUX1 transgenic mice develop mammary tumors of various histological types after a long latency." (PMID 24618719, 2014). "In this study, we presented evidence from transgenic mouse models, tissue culture systems and human breast cancer databases implicating the CUX1 and GLIS1 transcription factors in the autocrine activation of the Wnt/β-catenin pathway." (PMID 25217618, 2014). "The presence of an active p110 CUX1 species carrying an HA tag in tumor samples and tumor-derived cell lines led us to assess cathepsin L expression in mammary tumors from MMTV-p200, p110, and p75 CUX1 transgenic mice." (PMID 24618719, 2014). "Molecular analysis of mammary tumors from MMTV-p200 CUX1 mice revealed the presence activating Kras mutations in 45% of mammary tumors, suggesting that activated RAS and CUX1 cooperate in tumor formation." (PMID 24618719, 2014). "We investigated CUX1 expression and DNA binding activity in mammary tumors and normal mammary glands of age-matched transgenic littermates." (PMID 24618719, 2014). "Similar increases in nuclear β-catenin expression and TCF/β-catenin transcriptional activity were observed in Hs578T and MCF-7 human breast cancer cells upon ectopic expression of p110 CUX1." (PMID 25217618, 2014). "Overexpression of the Cut homeobox 1 gene, CUX1, inverselycorrelates with patient survival in breast cancers." (PMID 23590133, 2013). "In addition to CDKN1A, HEB and E2A co-occupy three TSG loci, APC, a haplo-insufficient tumor suppressor, ZMYND11 a chromatin reader and tumor suppressor in breast cancer and CUX1, a homeodomain transcription regulator and haploinsufficient tumor suppressor." (PMID 35401501, 2022). "MMTV-p110 CUX1 mice also developed mammary tumors with a similarly long latency." (PMID 34070180, 2021). "CUX1 stimulates migration and invasion by transcriptionally activating or repressing a series of target genes related to cell motility, including activating snail and slug and repressing E-cadherin, in breast cancer cells." (PMID 32547943, 2020). "Next, loss of heterozygosity (LOH) analyses confirmed LOH at 7q22 in a subset of breast cancer, uterine leiomyoma, and ovarian cancer, suggesting that genes in this region including CUX1 may function as tumor suppressors." (PMID 32547943, 2020).
breast cancer (continued). "Secondly, since only one third of the mammary tumors in MMTV-CUX1 transgenic mice exhibit high WNT expression, we hypothesized that other factors are needed, in addition to CUX1, for transcriptional activation of this pathway." (PMID 25217618, 2014). "As expected, CUX1 transgene mRNA was detected in all mammary tumors." (PMID 24618719, 2014). "The fact that one third or less of mammary tumors from MMTV-CUX1 transgenic mice exhibited elevated Wnt gene expression indicated that CUX1 alone is not sufficient to activate this pathway and provided an opportunity to identify other transcription factors that cooperate with CUX1 in this process." (PMID 25217618, 2014). "However, mutations within the Kras genes were identified in 5 out of 11 mammary tumors from MMTV-p200 CUX1 transgenic mice." (PMID 24618719, 2014). "CUX1 knockdown caused increased oxidative DNA damage and inhibited the proliferation of Hs578T mammary tumor cells, which harbor an HRASG12D oncogene, but not of Hs578Bst cells, which are normal mammary epithelial cells obtained from the same patient." (PMID 24618719, 2014). "Moreover, the important role of CUX1/FGF1/HGF signalling in promoting cell proliferation, migration and tube formation in vascular endothelial cells was strongly associated with the DPPA‐induced inhibition of tumour growth and angiogenesis in breast cancer." (PMID 30010249, 2018). "In MMTV-Cut like homeobox 1 (CUX1) transgenic mice, a mouse model used to study breast cancer development, GLIS1 was found to be highly expressed in a subset of breast tumors with elevated WNT expression." (PMID 35681527, 2022). "Cux/CDP/CUTL1/Cux-1 is another MARBP that is significantly increased in high-grade carcinomas and its expression is inversely correlated with breast cancer survival." (PMID 26325577, 2015). "We verified whether high WNT gene expression correlates with that of CUX1 and GLIS1 in human breast cancers." (PMID 25217618, 2014). "Since activation of the β-catenin pathway was observed in a fraction of mammary tumors from MMTV-CUX1 transgenic mice, we reasoned that it might require other transcription factors in addition to CUX1." (PMID 25217618, 2014).
neuroblastoma (19 papers, 2019 to 2025). Neuroblastoma (NB) is the most common solid, extracranial childhood tumor. "Studies have confirmed that the circRNA derived from Cux1, encoding protein P113, drives neuroblastoma (NB) progression by facilitating the trans-activation of ZRF1/BRD4." (PMID 39103807, 2024). "Another piece of literature revealed a role for circ-CUX1 in accelerating neuroblastoma progression through the miR-16-5p/DMRT2 pathway." (PMID 38282862, 2024). "Another group demonstrated that circ‐CUX1 accelerated the proliferation, invasion, migration, and glycolysis of neuroblastoma cells by targeting the miR‐16‐5p/DMRT2 signaling cascade." (PMID 35592755, 2022). "Another study in neuroblastoma has shown that the oncogenic circular RNA circ-CUX1 enhances tumorigenesis of neuroblastoma and their glycolysis through targeting miR-16-5p." (PMID 36348403, 2022). "CUX1 is independently related to poor outcomes, and patients with high circCUX1 expression had a lower survival probability in clinical neuroblastoma cases." (PMID 35592755, 2022). "Another study in xenograft model of neuroblastoma has shown that knock down of the miR-16-5p-targeting circ-CUX1 leads to reduction of tumor growth." (PMID 36348403, 2022). "In neuroblastoma, up-regulation in circ-CUX1 that sponges miR-16-5p has been correlated with advanced TNM stage, low differentiation grade and lymph node metastasis." (PMID 36348403, 2022). "circCUX1 interacted with EWS RNA-binding protein 1 (EWSR1) and facilitated EWSR1-mediated transactivation of MYC-associated zinc finger protein (MAZ), promoting the transcriptional of CUX1, glycolysis and neuroblastoma progression." (PMID 33643900, 2020). "More interestingly, a very recent study has demonstrated that CUX1 can generate a circular RNA (circ-CUX1) to promote tumor progression in neuroblastoma (NB)." (PMID 32547943, 2020). "circCUX1 (hsa_circ_0132813), consisting of exon 2 and partial intron 2 of CUX1, was localized in the nucleus and increased in neuroblastoma." (PMID 33643900, 2020). "The circ‐CUX1/EWSR1/MAZ axis emerges as a possible therapeutic target for neuroblastoma progression." (PMID 31709724, 2019). "For example, CUT-like homeobox 1 (CUX1)-generated circular RNA (circ-CUX1) enhances the trans-activation of MYC-associated zinc finger protein (MAZ) through EWS RNA-binding protein 1 (EWSR1), thereby promoting aerobic glycolysis and neuroblastoma progression." (PMID 39062737, 2024). "Circ‐CUX1 binds to the RRM region of EWSR1 and promotes MAZ transactivation, thereby altering the transcription of CUX1 and the association of other genes with neuroblastoma progression." (PMID 35592755, 2022). "circ-CUX1 binds to Ewing Sarcoma (EWS) RBP1 (EWSR1), resulting in transactivation of MYC-associated zinc finger protein (MAZ) and inhibiting glycolysis to suppress the progression of neuroblastoma." (PMID 33425493, 2021). "The circRNA, CUT-like homeobox 1 (CUX1), encodes a 113 amino acid protein (p113), which interacts with Zuotin-related factor 1 (ZRF1) and results in higher production of fatty acids, mitochondrial complex I activity, and therefore, aggressiveness and tumorigenesis of neuroblastoma (NB)." (PMID 37161350, 2023). "CUX1 acts independently on progression and poor outcome and is a promoter of ENO1, GPI, and PGK1 expression in neuroblastoma." (PMID 35592755, 2022). "Disrupting this circ-CUX1/EWSR1/MAZ axis suppresses glycolysis and the growth and metastasis of neuroblastoma cells in vivo." (PMID 36077650, 2022). "It has been reported that circ-CUX1 binds to EWSR1 and transactivates MAZ, which contributes to aerobic glycolysis and the progression of neuroblastoma." (PMID 33425493, 2021). "The expression of p113, a polypeptide originating from the circRNA of the CUX1 gene (hsa_circ_0005253) and reliant on an IRES element, was found to be highly elevated in neuroblastoma (NB) cells." (PMID 40717901, 2025).
neuroblastoma (continued). "Similarly, circ-CUX1 binds to EWS RNA-binding protein 1 (EWSR1) to promote its interaction with MYC-associated zinc finger protein (MAZ), transactivating MAZ, and modulating CUX1 expression to facilitate the metabolic reprogramming and progression of neuroblastoma (NB)." (PMID 36186139, 2022).